APEX2 (apurinic/apyrimidinic endodeoxyribonuclease 2)
Description:
Functions as a weak apurinic/apyrimidinic (AP) endodeoxyribonuclease in the DNA base excision repair (BER) pathway of DNA lesions induced by oxidative and alkylating agents. Initiates repair of AP sites in DNA by catalyzing hydrolytic incision of the phosphodiester backbone immediately adjacent to the damage, generating a single-strand break with 5'-deoxyribose phosphate and 3'-hydroxyl ends. Also displays double-stranded DNA 3'-5' exonuclease, 3'-phosphodiesterase activities. Shows robust 3'-5' exonuclease activity on 3'-recessed heteroduplex DNA and is able to remove mismatched nucleotides preferentially. Also exhibits 3'-5' exonuclease activity on a single nucleotide gap containing heteroduplex DNA and on blunt-ended substrates. Shows fairly strong 3'-phosphodiesterase activity involved in the removal of 3'-damaged termini formed in DNA by oxidative agents. In the nucleus functions in the PCNA-dependent BER pathway. Plays a role in reversing blocked 3' DNA ends, problematic lesions that preclude DNA synthesis. Required for somatic hypermutation (SHM) and DNA cleavage step of class switch recombination (CSR) of immunoglobulin genes (By similarity). Required for proper cell cycle progression during proliferation of peripheral lymphocytes (By similarity).
Synonyms: APE2; APEXL2; XTH2; ZGRF2
Tractability: PROTAC: UniProt records ubiquitination sites on it; ubiquitination databases record sites on it.
Gene: Protein-coding gene on chromosome X (55,000,331 to 55,009,057, forward strand). Ensembl gene ENSG00000169188.
Subcellular location: Nucleus; Cytoplasm; Mitochondrion
Subcellular location (Human Protein Atlas): Nucleoli fibrillar center; Nucleoplasm; Vesicles
Gene Ontology:
Molecular function: double-stranded DNA 3'-5' DNA exonuclease activity; protein binding; catalytic activity; DNA binding; endonuclease activity; nuclease activity; zinc ion binding
Biological process: base-excision repair; DNA repair
Cellular component: fibrillar center; mitochondrion; nucleoplasm; nucleus; cytoplasm
Homologues: Orthologues: chimpanzee APEX2 (99% identical), macaque APEX2 (96% identical), dog APEX2 (86% identical), pig APEX2 (84% identical), mouse Apex2 (79% identical), rat Apex2 (79% identical), guinea pig APEX2 (78% identical), rat Apex2l1 (73% identical), zebrafish apex2 (47% identical), tropical clawed frog apex2 (46% identical). Paralogues in human: APEX1 (14% identical).
Diseases named in the same sentence as APEX2 in open-access papers:
APEX2 is named in the same sentence as 35 diseases in open-access papers, as found by Europe PMC text mining. Sharing a sentence is not in itself a finding about the gene and the disease. The quoted sentences say what the papers report.
pancreatic cancer (7 papers, 2020 to 2025). "(C) Number of cell membrane proteins identified by mass spectrometry (>2 unique peptides, <1% FDR, found in both biological replicates) after treating 500,000 KP-4 pancreatic cancer cells with either free enzyme (APEX2 or HRP) or cell-tethered enzyme (DNA-APEX2 or WGA-HRP)." (PMID 35257663, 2022).
multiple myeloma (5 papers, 2019 to 2023). "An interesting new development is the finding that the BER-associated apurinic/apyrimidinic (AP) nucleases, APEX1 and APEX2, contribute in important ways to the regulation of HR in myeloma." (PMID 31139207, 2019). "Genetic and pharmacological inhibition of APEX1 and APEX2 inhibited HR activity in myeloma cells, using a mechanism that involved the ability of AP nucleases to regulate the expression of RAD51 recombinase." (PMID 31139207, 2019). "In contrast, APEX2 overexpression has been reported in liver cancer and myeloma." (PMID 33962398, 2021).
ovarian carcinoma (3 papers, 2020 to 2021). A malignant neoplasm originating from the surface ovarian epithelium. "Our findings on APEX2 are supported by evidence that this ZNF protein serves as a synthetic lethal target in BRCA1- and BRCA2-deficient colonic and ovarian cancer cell lines." (PMID 33962398, 2021).
chlamydial infection (1 paper, 2021). "We utilized the engineered ascorbate peroxidase, APEX2, which biotinylates proximal proteins in the presence of biotin-phenol and hydrogen peroxide, to test whether the BirA-identified protein candidates were in proximity to TmeA in the context of chlamydial infection." (PMID 33468693, 2021).
esophageal cancer (1 paper, 2018). A primary or metastatic malignant neoplasm involving the esophagus. "We show that transgenic as well as chemical suppression of AP nucleases inhibits RAD51 expression in MM as well as esophageal cancer (not shown) cells, whereas transgenic upregulation of APEX1 as well as APEX2 induces RAD51 expression." (PMID 30301882, 2018).
polio (1 paper, 2022). "Thus, the APEX2-GARG-1060 construct is fully functional in polio replication." (PMID 36306280, 2022).
virus infection (1 paper, 2019). "As proof of principle to demonstrate the APEX2 fusions were capable of detecting NPs during virus infection, we probed Vero-E6 cells in 96-well plates that had been infected with either MARV or EBOV." (PMID 31010013, 2019).
cancer (21 papers, 2012 to 2025). A tumor composed of atypical neoplastic, often pleomorphic cells that invade other tissues. "APEX2 expression is upregulated in several cancers, including kidney, breast, lung, liver, and uterine cancers." (PMID 33525741, 2021). "APEX2 genomic alterations are estimated to occur with a frequency of ~17% in 14 cancer types, based on data available at The Cancer Genome Atlas." (PMID 33525741, 2021). "We adopted a proximity-dependent labeling approach using an engineered ascorbate peroxidase (APEX2) system to determine how OGFOD1 affects cancer proliferation." (PMID 34298635, 2021). "The other important genes in this pathway like Abl1, Gml, Brca1, Zak, Xrcc5, Trex1, Pms1, Ccnu and Apex2 were also up regulated in the cancer cells." (PMID 22321936, 2012). "Subsequently, the B7-H3–APEX2 or APEX2 proteins were incubated with immune or cancer cells." (PMID 40004194, 2025). "We constructed APEX2-tagged OGFOD1 (OGFOD1-APEX2) and confirmed nuclear localization by immunostaining in HEK293T cell line to find target proteins that regulate cancer growth through OGFOD1." (PMID 34298635, 2021).
infection (9 papers, 2017 to 2025). The state of being infected such as from the introduction of a foreign agent such as serum, vaccine, antigenic substance or organism. "Whether endogenous GBF1 associates with stress granules upon infection, or this phenotype is specific to the truncated APEX2-GARG-1060 construct requires further investigation." (PMID 36306280, 2022). "Leveraging this advance, we infected cells with a C. trachomatis L2/434 strain engineered to express flag-tagged Inc-APEX2 fusion proteins, to enable the labeling of inclusion membrane interacting proteins in live cells, at multiple times during infection." (PMID 30943267, 2019). "The sdAb–APEX2 fusions also enabled live Marburgvirus and Ebolavirus detection 24 h post-infection of Vero E6 cells within a BSL-4 laboratory setting." (PMID 31010013, 2019). "To test for this occurrence, we infected HeLa cells with purified chlamydial transformants of IncATM-APEX2, IncF-APEX2, or APEX2 alone and induced expression of the constructs with the indicated concentrations of aTc 7 h post-infection." (PMID 28261569, 2017). "Interestingly, these APEX2 data suggest that TmeA can maintain or reestablish an interaction with N-WASP during later stages of infection." (PMID 33468693, 2021).
tumor (8 papers, 2020 to 2025). "For instance, genes such as AURKA, APEX2, CCNE1, and FOXM1 have been reported to be associated with tumor resistance." (PMID 40098976, 2025).
APEX2 also shares sentences with these, for which no sentence is quoted: liver cancer (4 papers); melanoma (3); prostate carcinoma (3); breast carcinoma (2); kidney cancer (2); lung carcinoma (2); meningioma (2); uterine cancer (2); acute kidney injury (1); autoimmune disease (1); B-cell lymphomas (1); B-cell neoplasm (1); bladder cancer (1); breast tumors (1); epilepsy (1); hearing loss (1); hematologic cancers (1); hepatocellular carcinoma (1); lentivirus infection (1); metastatic melanoma (1); monoclonal gammopathy of undetermined significance (1); osteoarthritis (1); prostate tumor (1); sarcoma (1); triple-negative breast carcinoma (1).